UCP3 (uncoupling protein 3)
Diseases named in the same sentence as UCP3 in open-access papers (continued):
Sharing a sentence is not in itself a finding about the gene and the disease.
prediabetes (2 papers, 2018 to 2025). "The findings suggested a significant association between UCP3 rs1800849 and prediabetes in this population." (PMID 29529994, 2018). "In the current study, we used bioinformatics analyses to identify and select a set of variants in the UCP2/UCP3 region to determine the association between UCP2/UCP3 and prediabetes or T2DM in a Chinese population." (PMID 29529994, 2018). "The haplotypes, gene-environmental interaction and association between genetic variants of UCP2 and UCP3 and prediabetes or T2DM were explored." (PMID 29529994, 2018). "In conclusion, rs1800849 in UCP3 were significantly associated with prediabetes in a rural Chinese population." (PMID 29529994, 2018). "The study was to examine the associations of genetic variants of UCP2 and UCP3 with prediabetes and T2DM in a rural Chinese population." (PMID 29529994, 2018). "After the adjustment for possible covariates, the A allele of rs1800849 in UCP3 was significantly associated with prediabetes (aORAA vs GG = 1.68, 95% CI: 1.02–2.78), and the association was also significant under the recessive model (aOR AA vs GA + GG = 1.64, 95% CI: 1.02–2.66)." (PMID 29529994, 2018). "Rs1800849 in UCP3 was significantly associated with prediabetes." (PMID 29529994, 2018). "In this study, three SNPs of UCP2 and six SNPs of UCP3 were genotyped and the associations between these SNPs and T2DM or prediabetes were evaluated in a rural Chinese population." (PMID 29529994, 2018). "Little is known with regard to the association between UCP2/UCP3 polymorphisms and T2DM or prediabetes in Chinese population." (PMID 29529994, 2018).
asthenozoospermia (1 paper, 2023). "Since the loss of motility induced by genipin is potentially mediated by UCP3 inhibition, we sought to evaluate if UCP3 expression was altered in the spermatozoa of men with asthenozoospermia." (PMID 36829970, 2023).
autoimmune disease (1 paper, 2020). A disorder resulting from loss of function or tissue destruction of an organ or multiple organs, arising from humoral or cellular immune responses of the individual to their own tissue constituents. "The observation that Ucp3 ablation alters the Th17:Treg cell balance in vivo as well as in vitro suggests that UCP3 is a potential target for the treatment of Th17 cell-mediated autoimmune diseases." (PMID 33211703, 2020).
Autoimmunity (1 paper, 2020). The occurrence of an immune reaction against the organism's own cells or tissues. "In light of these data, the targeting of Ucp3 to modulate autoimmunity warrants further investigation." (PMID 33211703, 2020).
babesiosis (1 paper, 2021). Babesiosis refers to a condition caused by microscopic parasites that infect the red blood cells. "Several mitochondrial proteins, including the uncoupling protein 3 involved in oxidative phosphorylation, were also found in the urinary proteome of dogs with babesiosis and kidney injury." (PMID 34603243, 2021).
breast carcinoma (1 paper, 2020). "Inhibition of UCP2 and UCP3 increased ROS formation, reduced viability via autophagic cell death, and increased the toxic effects of chemotherapeutics in breast cancer cells while high UCP2 levels confer a poor prognosis to breast cancer patients." (PMID 33520711, 2020).
developmental delay (1 paper, 2020). "Four genes (UCP2, UCP3, SCAPER, and TSHR) are related to the body weight (HP:0004324 and HP:0004323), and four genes (C2CD3, UCP2, ZMYND11, and TSHR) are involved in modulating the phenotype of globe developmental delay (HP:0001263)." (PMID 32973871, 2020).
diabetic cardiomyopathy (1 paper, 2023). Diabetic cardiomyopathy is a disorder of the heart muscle in people with diabetes. "Combined, the decreased cardiac expressions of Pdk4 and Ucp3, reduced cardiac glycogen content, and reversion of diabetic cardiomyopathy in O304-treated STZ mice provide evidence that O304 restores cardiac metabolic flexibility and glucose oxidation, i.e., cardiac efficiency, in these mice." (PMID 37626210, 2023).
endotoxemia (1 paper, 2015). "Similarly, myocardial mRNA content of both UCP2 and UCP3 were increased in LPS-induced endotoxemia in rats, and increased myocardial mRNA and protein expression of UCP2 was observed in a canine model of endotoxin-induced shock associated with decreased phosphocreatine/ATP ratios." (PMID 26247933, 2015).
hypothyroidism (1 paper, 2023). Abnormally low levels of thyroid hormone. "The expression of Ucp3 in the skeletal muscle of hypothyroidism rats is significantly lower than that of rats with normal thyroid function." (PMID 38002992, 2023).
insulin-dependent diabetes (1 paper, 2018). "In fact, there is considerable evidence for increased myocardial UCP3 levels with high-fat feeding and with type 1 diabetes." (PMID 30374710, 2018).
Myalgia (1 paper, 2017). "Although mitochondrial genes did not figure prominently among our DEGs, individual mitochondrial genes, including mitochondrial fission factor (MFF) and uncoupling protein-3 (UCP3) exhibited markedly altered expression in muscle of patients with statin-associated myalgia." (PMID 28771594, 2017).
renal cell carcinoma (1 paper, 2015). "In conclusion, hypoxia/reoxygenation-tolerant PT cultures as well as renal cell carcinoma upregulate UCP-3 uncoupling protein in the inner mitochondrial membrane." (PMID 26304588, 2015). "UCP-3 protein was also upregulated in the majority of specimens from human renal cell carcinoma (RCC) as compared to the protein abundance of co-resected normal kidney tissue." (PMID 26304588, 2015).
rhabdomyosarcoma (1 paper, 2019). A rare aggressive malignant mesenchymal neoplasm arising from skeletal muscle. "Polyclonal antibodies can cross-react with structurally-related molecules so it is possible that staining with the anti-UCP1 antibody of malignant tumour cells in some non-adipose sarcomas could represent a cross-reaction with a UCP1 homologue, such as UCP2 and/or UCP3 in rhabdomyosarcomas." (PMID 31114671, 2019).
Tachycardia (1 paper, 2020). A rapid heartrate that exceeds the range of the normal resting heartrate for age. "Subjecting cardiac UCP3 knockout (UCP3–/–) mice to I/R injury produced twofold larger infarcts, a high propensity for ventricular tachycardia, and excessive ROS generation when compared to WT mice." (PMID 33585462, 2020).
vitamin D deficiency (1 paper, 2020). A nutritional condition produced by a deficiency of VITAMIN D in the diet, insufficient production of vitamin D in the skin, inadequate absorption of vitamin D from the diet, or abnormal conversion of vitamin D to its bioactive metabolites. "Moreover, vitamin D deficiency up-regulated the expression of uncoupling protein 3 (Ucp3) in white adipose tissue (WAT) and brown adipose tissue (BAT)." (PMID 32452516, 2020). "Moreover, vitamin D deficiency up-regulated the expression of Ucp3 in WAT and BAT." (PMID 32452516, 2020).
cancer (19 papers, 2002 to 2025). A tumor composed of atypical neoplastic, often pleomorphic cells that invade other tissues. "Overexpression of UCP1 in brown adipose tissue and UCP3 in skeletal muscle exacerbates weight loss in models of cancer cachexia." (PMID 34627389, 2021). "We have shown that UCP-3 mRNA levels are increased in muscle only when weight loss is associated with cancer." (PMID 11875702, 2002). "Mean UCP-3 levels, however, were over five times higher in the cancer patients with weight loss group than in controls." (PMID 11875702, 2002). "Higher numbers of reactive oxygen species (ROS) build-up in the mitochondria and mitochondria uncoupling protein 3 (UCP3) are activated from numerous scenarios characterized by skeletal muscle deterioration, cancer, and glucocorticoid (GCs) administration." (PMID 34828008, 2021). "Recent studies have found that high levels of UCP2 and UCP3 appear to be beneficial for cancer cells as well as influence mitochondrial structural adaptation." (PMID 33520711, 2020). "The present study establishes a molecular mechanism for UCP3-induced cancer prevention, and shows that enforced UCP3 expression blocks Akt activation in mouse and human keratinocytes." (PMID 26310111, 2015). "Analysis of UCP3 expression in the Oncomine database revealed 17 studies in which UCP3 was among the top 10% of downregulated genes in cancer tissues compared with normal tissue controls." (PMID 26310111, 2015). "The aberrant expression of genes involved in mitochondrial biogenesis (PGC-1β) and uncoupling (UCP3) that we observed in this clinically relevant cancer cachexia model, are in agreement with previously reported data." (PMID 23817738, 2013). "The presently observed upregulation of UCP3 in cancer cachectic animals agrees with our mitochondrial coupling index difference in suggesting the presence of mitochondrial uncoupling in cachectic mice and corroborates previous findings." (PMID 23817738, 2013). "In fact, increased expression of UCP1 in BAT and UCP2 and UCP3 in skeletal muscle have been shown in several murine models of cancer cachexia." (PMID 24281083, 2010). "If the up-regulation of UCP-3 in skeletal muscle in human cancers does result in increased energy expenditure and result in weight loss, this offers potential new targets for therapeutic intervention." (PMID 11875702, 2002). "Thus far, UCP-1, UCP-2, and UCP-3 have been studied in a very limited way in cancer cachexia, and only their expression has been measured and identified, but no drug or molecule has been developed." (PMID 36900198, 2023). "Over expression of UCP-3 in the skeletal muscle of human cancer patients might contribute to increase energy expenditure and thus to weight loss." (PMID 11875702, 2002). "Thus, the high levels of UCP2 and UCP3 observed in the cancer spheroids could contribute to the regulation of ROS levels, survival, and proliferation." (PMID 33520711, 2020). "K5-UCP3/K5-Akt mice also formed more carcinomas than wild-type mice, however they still showed a significant reduction in carcinoma formation compared with K5-Akt mice, suggesting that UCP3 may also inhibit tumour progression, even in the context of Akt overexpression." (PMID 26310111, 2015). "In the cancer without weight loss group, mean UCP-3 levels were similar to controls." (PMID 11875702, 2002). "While UCP1, UCP3, SLC25A27, and SLC25A14 were frequently downregulated in most cancers, UCP2 showed consistent upregulation, indicating divergent functional roles in oncogenesis." (PMID 41403699, 2025). "These consistent expression patterns suggest that UCP2 may function as an oncogene in diverse cancer contexts, while UCP1, UCP3, SLC25A27, and SLC25A14 are potentially involved in tumor-suppressive mechanisms." (PMID 41403699, 2025).
cancer (continued). "The upregulation of UCP-1, UCP-2, and UCP-3 in BAT and UCP-2 in the skeletal muscle and liver suggested that UCPs were involved in utilizing an excess of fat to induce heat production and thereby increased catabolism and energy expenditure in cancer cachexia." (PMID 36900198, 2023). "Notably, UCP3 is almost exclusively expressed in skeletal muscle, and evidence suggests that cancer cachexia leads to the induction of UCP2 and UCP3 via TNF‐α." (PMID 36251564, 2022). "However, t it has been reported that the expression of UCP3 was significantly increased, but UCP2 expression was not significantly increased in the skeletal muscle of cancer-bearing mice." (PMID 38630690, 2024).
tumor (13 papers, 2009 to 2025). "An activation of UCP2 and UCP3 gene expression associated with an increase of catalase activity has previously been reported in atrophied gastrocnemius muscles of tumour-bearing rats." (PMID 19462004, 2009). "Studies investigating the expression and function of UCP1 and its homologs (UCP2 and UCP3) in various tumor types have yielded heterogeneous results." (PMID 40983641, 2025). "The study concluded that the overexpression of UCP-2 and UCP-3 in the skeletal muscle was due to the anorexia induced by the burden of the tumor." (PMID 36900198, 2023). "We believe that the data make a strong case for Akt inhibition as a central mechanism in UCP3-induced resistance to tumour formation." (PMID 26310111, 2015). "As tumor hypoxic cells accelerate malignancy and drug resistance, targeting UCP-3 may help develop anticancer therapies." (PMID 36900198, 2023). "Analyses of UCP mRNA levels in different stages of OC showed that UCP3 and UCP4 have distinct expression patterns in different tumor stages, indicating that UCP3 and UCP4 may participate in tumor progression." (PMID 35090503, 2022). "The majority of tumor specimens showed various levels of UCP-3 protein abundance that was on average significantly higher than in the non-cancerous renal samples indicating upregulation of UCP-3 during tumor development." (PMID 26304588, 2015). "Since tumor hypoxia promotes both, malignancy and therapy resistance, UCP-3 protein expression might be a prognostic and predictive marker in human neoplasms." (PMID 26304588, 2015). "UCP1, UCP2, UCP3 and UCP5 expression levels correlated with a favorable prognosis and tumor progression." (PMID 35090503, 2022). "UCP1, UCP3, SLC25A27, and SLC25A14 showed significantly lower expression in most tumor tissues." (PMID 41403699, 2025). "Conversely, the frequent downregulation of other UCP family members, such as UCP3 and SLC25A27, across tumors suggests their potential roles as tumor suppressors, although this remains speculative without functional validation." (PMID 41403699, 2025).
metabolic disease (5 papers, 2016 to 2025). A congenital disorder (due to inherited enzyme abnormality) or acquired (due to failure of a metabolically important organ) disorder resulting from an abnormal metabolic process. "PPARs are the link between FA (or their derivatives), metabolic diseases, and tissue-specific expression of UCP2 and UCP3." (PMID 27399675, 2016). "RS may alleviate metabolic disorders, by inhibiting body weight increase, reducing fasting blood glucose levels, and ameliorating insulin tolerance in HF diet-induced obese C57BL/6 mice through the increase of UCP3 and PPARs." (PMID 28507819, 2017).
cardiac diseases (2 papers, 2009 to 2024). "Increased expression of FAT/CD36, FATP1, UCP2 and UCP3 have all been implicated in development of lipotoxic heart disease." (PMID 19390571, 2009). "Notably, the absence of UCP3 led to significant mitochondrial structural changes, particularly in older mice, underscoring the potential of S1QEL as a therapeutic strategy in mitochondrial-related cardiac diseases." (PMID 39763794, 2024).
degenerative disease (1 paper, 2012). "But for UCP2 and UCP3, there is a consensus that the primary function of UCP2 and UCP3 is to attenuate mitochondrial production of free radical to protect against oxidative damage, degenerative disease and aging rather than to promote gross thermogenesis or energetic inefficiency." (PMID 22313584, 2012).
UCP3 also shares sentences with these, for which no sentence is quoted: Hyperinsulinemia (4 papers); cardiovascular diseases (3); Glucose intolerance (3); colon carcinoma (2); acute kidney injury (1); allergic disease (1); aortic regurgitation (1); Arrhythmia (1); atherosclerosis (1); Cirrhosis (1); dilated cardiomyopathy (1); fibrosis (1); head and neck squamous cell carcinoma (1); hepatocellular carcinoma (1); hyperlipidemia (1); hypertriglyceridemia (1); infection (1); leukemia (1); liver failure (1); multiple sclerosis (1); myopathies (1); papilloma (1); polycystic kidney disease (1); prostate carcinoma (1); prostatic neoplasms (1); psoriasis (1); sarcopenia (1); schizophrenia (1); skin tumour (1); Ventricular arrhythmia (1).